CDCP1 (CUB domain containing protein 1)
Diseases named in the same sentence as CDCP1 in open-access papers (continued):
Sharing a sentence is not in itself a finding about the gene and the disease.
tumor (96 papers, 2010 to 2026). "As a transmembrane glycoprotein and substrate of Src family kinases, CDCP1 has been implicated in tumor progression and metastasis in colorectal, ovarian, lung, and renal cancers." (PMID 41488282, 2026). "The intensity, staining percentage, and product of the intensity and percentage of CDCP1 were all associated with tumor grade with high statistical significance." (PMID 36862682, 2023). "Not only did we prove the association between CDCP1 with the tumor grade in UC tissue assay, but also elucidated its involvement in the migration/invasion abilities, MMP secretion, and colony formation of UC cells." (PMID 36862682, 2023). "After adjusting for age, gender, tumor stage, site, and standard therapy in a multivariate analysis, high CDCP1 expression was an independent risk factor for lung recurrence." (PMID 31461438, 2019). "In our analysis of vascular lacunae, a trend of association was revealed between PDGFRβ in tumor cells in vascular-like structures and CDCP1 expression (p = 0.0795; Fisher’s exact test)." (PMID 29792166, 2018). "Growth factor receptors that are involved in tumor progression have been implicated in CDCP1 overexpression." (PMID 29792166, 2018). "Elevated CDCP1 expression in tumour biopsies has been associated with reduced patient survival in pancreatic, lung and renal cell carcinoma." (PMID 25301083, 2014). "Many tumor cell lines produce a CDCP1 splice variant that is secreted and encodes the first 341 amino acids, with the carboxy-terminal two amino acids being variant specific." (PMID 23300860, 2012). "Notably, CUB-domain-containing protein 1 (CDCP1) from radiation-induced sEVs was identified as a novel tumor-associated antigen, contributing to their capability of inducing tumor immunogenicity." (PMID 40103824, 2025). "Integrating these models with spatial and single-cell transcriptomic profiling could clarify whether distinct CAF subsets (myCAF, iCAF, apCAF) or immune compartments preferentially associate with CDCP1-high tumor niches." (PMID 41301830, 2025). "Moreover, CDCP1 was found to be a novel tumor-associated antigen in EVs from irradiated tumor cells, which can trigger antitumor immunity against primary tumors and experimental lung metastases by enhancing the infiltration of CD8+ and CD4+ T cells." (PMID 38814362, 2024). "Furthermore, we observed high levels of factors associated with tumor cell proliferation (CDCP1, EpCAM, EGFR, and PDGFB)." (PMID 38942797, 2024). "First, increased CDCP1 expression in UC tissues was associated with tumor grade." (PMID 36862682, 2023). "Proteolysis, along with overexpression, has been associated with the tumor-promoting functions of CDCP1, which involve phosphorylation of intracellular tyrosine residues and initiation of downstream signaling pathways associated with loss of adhesion, increased migration, and anoikis." (PMID 35166238, 2022). "Up-regulation of CDCP1 has been implicated in tumor progression." (PMID 33574034, 2021). "Also, consistent with effects on tumor burden caused by 10D7, stable silencing of CDCP1 markedly reduced tumor burden of subcutaneous xenografts of PANC-1 and TKCC05 cells compared with xenografts of these cells stably transduced with scramble control vectors." (PMID 32226543, 2020). "CDCP1 is a type 1 transmembrane protein with a large extracellular domain that is upregulated in many tumour types, and has been linked functionally to anoikis resistance, tumour invasion and metastasis." (PMID 26227951, 2015). "Given the immunosuppressive and stromal-rich microenvironment of PDAC, we hypothesized that CDCP1 expression reflects both tumor-intrinsic features, such as mutational burden and oncogenic pathway activation, and microenvironmental remodeling involving immune and stromal components." (PMID 41488282, 2026).
tumor (continued). "In preclinical studies, CDCP1-targeted therapies, including ADCs, radiolabeled antibodies, and bispecific T-cell engagers, have suppressed tumor growth in PDAC and other solid tumors." (PMID 41488282, 2026). "In particular, antibodies specific for cleaved CDCP1 (c-CDCP1), a neoepitope specific to tumor cells, have shown high specificity and minimal off-target toxicity." (PMID 41488282, 2026). "CDCP1 is a single-pass transmembrane glycoprotein functioning as a central signaling hub promoting tumor proliferation, invasion, and metastasis." (PMID 41488282, 2026). "Integrated analysis of RNA sequencing and NSUN2 RIP-seq identified several candidate target genes (including STC1, CDCP1, FOSL1, and Serpine1) associated with tumor invasion and neuronal interactions 22-25." (PMID 41356184, 2026). "Antibody-based therapies targeting CDCP1 are currently being investigated in preclinical settings, demonstrating promise in inhibiting tumor growth and metastasis." (PMID 40892739, 2025). "It has been reported that CDCP1 regulates tumor progression during metastasis through c-Src/PKCδ pathway and FAK/PI3K/AKT signaling." (PMID 40892739, 2025). "Immunohistochemistry on a CRC tissue microarray further validated this observation: tumor epithelium exhibited stronger membrane CDCP1 staining than adjacent normal mucosa, and H-scores were markedly increased in tumors (p < 0.001)." (PMID 41301830, 2025). "The downregulation of cell adhesion proteins (ITGB1, LGALS3, LGALS3BP, SDCBP, PODXL, CDCP1) further suggests a potential impact on tumor cell attachment, migration, and invasion, contributing to the anti-metastatic effects of TSA." (PMID 40429900, 2025). "In parallel, CDCP1-high tumor cells condition fibroblasts toward a myofibroblastic, pro-tumor phenotype (α-SMA, FAP, PDGFRβ, S100A4 upregulation), linking a tumor-intrinsic epigenetic program to stromal reprogramming." (PMID 41301830, 2025). "For example, glycoconjugated palladium complex (Pd‐Oqn), a small compound, was shown to reduce tumor growth and metastasis by blocking the interaction of phosphorylated CDCP1 and PKC γ." (PMID 37013960, 2023). "Blocking CDCP1 using antibodies or small molecule inhibitors has been shown to effectively attenuate tumor development." (PMID 37013960, 2023). "Although CDCP1 cleavage is necessary for tumor aggressiveness, 8PN majorly reduced the full‐length CDCP1 proteins." (PMID 37013960, 2023). "High binding affinity of antibodies against the cleavage sites of CDCP1 was demonstrated to decelerate CDCP1‐driven tumor development." (PMID 37013960, 2023). "A comprehensive analysis of the expression level of CDCP1, clinicopathological grade and tumor TNM stage concluded that the expression level of CDCP1 varied significantly between different TNM stages." (PMID 37469398, 2023). "The same group also showed that CDCP1 is moderately or highly expressed in most of the BCa samples (n = 33) when compared to para-tumor controls and correlated CDCP1 expression with BCa progression." (PMID 36593286, 2023). "The results indicate the potential utility of CDCP1 as a useful biomarker to differentiate tumor and normal tissue in the diagnosis using tissue specimens of UC patients." (PMID 36862682, 2023). "According to the intensity and proportion of CDCP1 positive expression in the cytoplasm of tumor cells, CDCP1 was categorized into high and low expression groups." (PMID 37469398, 2023). "We also demonstrated that the LCIIAR/hsa-miR184/SLC16A3/CDCP1 network regulates SLC16A3/CDCP1 overexpression in and is associated with poor prognosis in this tumour." (PMID 35860557, 2022). "First, we compared the expression levels of CDCP1 in tumor and paratumor samples using the TCGA, the CPTAC, and the in-house cohorts." (PMID 36090897, 2022). "The tumor tissues with high CDCP1 expression showed a specific immunophenotype, with prominent M2 macrophages (P = 0.007)." (PMID 35410293, 2022).
tumor (continued). "Compared with paratumor tissue, CDCP1 was remarkably upregulated in the tumor tissues at both mRNA and protein levels." (PMID 36090897, 2022). "The results showed that the expression of CDCP1 increased with increasing tumor grade and that the overexpression of CDCP1 correlated with a poor prognosis." (PMID 35410293, 2022). "CDCP1 has been revealed to be significantly dysregulated in tumor tissues and accelerates progression in several malignancies." (PMID 36090897, 2022). "Treatment of mice harboring subcutaneous Fc1245 c-CDCP1 tumors with 1 or 2 400 μCi doses of 177Lu-IgG58 resulted in significantly reduced tumor volume compared with vehicle control, with the 2-dose regimen approaching tumor stasis." (PMID 35166238, 2022). "To investigate the underlying mechanism by which depletion of Toll‐7 suppressed RasV12/lgl−/−‐induced tumour growth, we checked cell death and cell proliferation by anti‐cDcp‐1 and anti‐phospho‐Histone H3 (pH3) staining, respectively." (PMID 35050535, 2022). "In contrast, we observed weaker tumor localization of 89Zr-IgG12 and more widespread off-tumor signal, indicating a higher presence of fl-CDCP1 in healthy tissues." (PMID 35166238, 2022). "Expression of AXL and CDCP1 in tumor samples was examined by immunohistochemical (IHC) analysis after tumors were surgically resected in 6 patients (#1, #2 with wild-type EGFR; #3, #4 with EGFRdel19; #5, #6 with L858R EGFR) before chemotherapy." (PMID 35643725, 2022). "Functionally, CDCP1 works upstream of Src and PKCδ to promote tumor cell motility and has also been reported to be involved in a variety of other tumorigenic signaling pathways, including EGFR and HIF." (PMID 35166242, 2022). "Statistically significant high tumor uptake of the radio-labelled antibody 89Zr-10D7 was found in two CDCP1-expressing CRC mouse models at late imaging time points with specificity indicated on protein silencing and epitope blocking models." (PMID 34621145, 2021). "Twice weekly measurement of xenograft volume indicated that tumor growth was unaffected by silencing of CDCP1." (PMID 34621145, 2021). "CDCP-1 regulates cell-to-cell adhesion and interacts with carcinogenic pathways, which promote tumor invasiveness and metastasis." (PMID 34885196, 2021). "Blocking CDCP1 dimerization in TNBC tumor cells by expressing the released component of cleaved CDCP1 significantly hampers LD abundance and metastatic potential in TNBC cells." (PMID 32296646, 2020). "As compared with CDCP1– cells from muKras tumor cells (DKs5 and HK2-10), the matched CDCP1+ fraction expressed lower levels of markers for cell proliferation, including Ki67, PCNA, and MCM2." (PMID 31461438, 2019). "In a separate cohort of 52 cases with stage II or III muKras CRCs, we examined the relationship between patient responses to neoadjuvant chemotherapy and CDCP1 mRNA level using prechemotherapeutic tumor biopsies." (PMID 31461438, 2019). "Analysis of muKras tumor cells using Hoechst plus pyronin Y staining showed that >90% of the CD133+ CDCP1+ fraction was in the G0 phase, whereas most CD133+ CDCP1– and CD133– fractions were actively cell cycling (<47% in the G0 phase)." (PMID 31461438, 2019). "Blocking CDCP1 activation by overexpressing the secreted extracellular portion of cleaved CDCP1 reduces tumor growth and metastasis in TNBC cell-derived xenografts (MDA-MB-231 and UCI-082014)." (PMID 31324052, 2019). "Because stem-cell signature expression in various tumor correlates inversely with outcome, we proposed that the degree of CDCP1 at the gene or protein level relates to the size of the clinically essential pool that can cause relapse." (PMID 31461438, 2019). "Nonetheless, we saw tumor localization of our CDCP1 antibodies in mouse xenograft models for PDAC, and MEK-dependent expression providing mechanistic validation in vivo." (PMID 29359686, 2018).
tumor (continued). "We tested the ability of one of our recombinant CDCP1 antibodies to selectively deliver a cytotoxic payload to mutant KRAS tumor cells." (PMID 29359686, 2018). "Recently, we proposed the transmembrane protein CUB domain-containing protein-1 (CDCP1), which is overexpressed in TNBCs and involved in tumor progression, as a new therapeutic target for TNBCs." (PMID 29792166, 2018). "About PDGFRβ expression in tumor and vascular lacunae according to CDCP1 levels, 72.4% (21/29) of PDGFRβ-positive cases in tumor nests were CDCP1-positive (p = 0.0429; Fisher’s exact test)." (PMID 29792166, 2018). "(i) Quantification of tumor specific bio-distribution of the CDCP1 89Zr-Fab in tumor-bearing nu/nu mice (n = 5 per treatment arm) confirms the trends observed by microPET imaging." (PMID 29359686, 2018). "The mechanisms driving CDCP1 over-expression are not fully understood, although several stimuli derived from tumor microenvironment, such as factors present in Wound Healing Fluids (WHFs), reportedly increase CDCP1 levels." (PMID 29792166, 2018). "Images over time show the tumor specific expression of CDCP1, as well as the persistent binding of the Fab to the tumor over 24 hr (Left)." (PMID 29359686, 2018). "In contrast, 50% of tumor samples showed higher levels of CDCP1 in tumor cells compared to expression in normal cells from these samples." (PMID 28537886, 2017). "Suppression of CDCP1 reduces tumor metastasis in vivo, demonstrating that blocking the function of CDCP1 influences tumor progression." (PMID 28537886, 2017). "The rise in CDCP1 mRNA and protein levels in TNBC cell lines on treatment with postsurgery WHFs, which mimic a protumor microenvironment, implicates CDCP1 in driving the aggressiveness of this tumor subtype." (PMID 27626701, 2016). "Tumors were considered positive when ≥ 10% of tumor cells showed membrane reactivity (mean CDCP1-positive tumor cells/section = 52%, range 10% to 100%); 57% (57/100) of cases were CDCP1-positive, 63% (36/57) of which expressed CDCP1 in ≥ 50% of tumor cells." (PMID 27626701, 2016). "In clear cell renal cell carcinoma (ccRCC) cells under hypoxic conditions, hypoxia-inducible factor (HIF)-2α induces the expression and activation of CDCP1, which relays pro-invasion and pro-tumor growth signals via PKCδ." (PMID 26973855, 2016). "Our assessment of CDCP1 expression in an FFPE tissue array demonstrated a modest decrease in tumor compared to normal, consistent with an earlier report." (PMID 26497208, 2015). "Functionally, CDCP1 likely provides a basal activity that enforces anchorage-dependent growth since ablation of CDCP1 expression promotes tumor metastasis." (PMID 26497208, 2015). "We propose that glycosylation of CDCP1 dictates cell surface presentation and proteolytic processing to drive the functional switch between tumor suppressor and tumor promoter activities." (PMID 26497208, 2015). "We observed variation in the intensity of CDCP1 expression and a reduction in the median staining intensity in tumor regions, consistent with an earlier report." (PMID 26497208, 2015). "Increased sialylation and cell surface presentation of CDCP1 signals a transition between epithelial and tumor cell expression." (PMID 26497208, 2015). "CDCP1 is a cell surface transmembrane protein that is widely expressed on many cell types, but also upregulated on many tumour cells and cell lines." (PMID 26227951, 2015). "The high content multi-parametric screen performed on PC-3 cells included several of the anti-CDCP1 DARPin-Fcs that were isolated by phage selections against the NSCLC tumour cells." (PMID 26227951, 2015). "The relative expression of full-length CDCP1 correlated with the metastatic potential of syngeneic cell models and an increase in surface membrane expression of CDCP1 was observed in tumor compared to adjacent normal prostate tissues." (PMID 26497208, 2015).
tumor (continued). "We saw no efficacy from antibody treatment alone in inhibiting growth of this patient-derived tumour model, in contrast to similar studies performed using other CDCP1 antibodies in cell line xenograft models." (PMID 26227951, 2015). "A lower differentiation grade of donor material correlated with a higher CDCP1 mRNA expression level in the respective tumour model." (PMID 22433494, 2012). "We report here that KAI1 acts in the process of tumor malignancy and angiogenesis by profoundly suppressing metastasis via inhibition of CDCP1-enhanced Src activation and functional activation of VHL." (PMID 22390300, 2012). "Although expression and phosphorylation of CDCP1 have been investigated in many tumor cell lines, the CDCP1 features responsible for transformation have not been fully evaluated." (PMID 23300860, 2012). "These pathways are known to contribute to immune exclusion and desmoplasia in PDAC, raising the hypothesis that CDCP1 may modulate multiple aspects of tumor progression." (PMID 41488282, 2026). "Collectively, these data show that therapeutic blockade of the SMYD3/CDCP1 axis disables tumor-promoting CAF activation, restrains hepatic metastatic outgrowth, and sensitizes CRC to oxaliplatin, supporting this axis as a tractable target to improve chemotherapy response." (PMID 41301830, 2025). "Considering that hypoxia‐inducible factor (HIF)‐1α drives the resistance of tumor cells to ferroptosis and CDCP1 is a downstream target gene of the HIF‐1/2 pathway, we speculate that the hypoxic TME may be associated with CDCP1+FTL+ CAFs." (PMID 40019403, 2025). "CD318 (CUB Domain-Containing Protein 1), a 140 kD cell surface transmembrane glycoprotein, has been implicated in various cellular processes, including tumor progression, metastasis, and interaction within the tumor immune microenvironment." (PMID 40725832, 2025). "Importantly, the tumor microenvironment induces CDCP1 activation via cleavage of its extracellular domain, revealing an epitope that can be targeted therapeutically." (PMID 40908298, 2025). "In addition, the expression of some tumor-related inflammatory factors, such as CDCP1 and TNFRSF9, are upregulated in AAA." (PMID 40599317, 2025). "Furthermore, the CUB domain-containing protein 1 (CDCP1) is a transmembrane protein that serves as a substrate for SRC family kinases and can cause tumor progression." (PMID 38622735, 2024). "The available literature demonstrated that CDCP1 might have an immunoregulatory function that is not only relevant to tumor biology, but also potential therapeutic applications in patients with neuroinflammatory conditions and autoimmune endocrine disorders." (PMID 39314522, 2024). "CDCP1 serves as a marker for tumor progression and also accelerates tumor metastasis." (PMID 39497803, 2024). "Previous research has demonstrated that CDCP1 plays a vital role in tumor metastasis and invasion." (PMID 37469398, 2023). "Overexpression of endogenous CD6 ligands (i.e., CD166/ALCAM, CD318/CDCP1, and CD44) is associated with tumour events, so the use of CD6-based CARs may broaden the spectrum of treatable tumours." (PMID 38139340, 2023). "However, there was markedly elevated expression of both AXL and CDCP1 in recurrent tumor after treatment with osimertinib." (PMID 35643725, 2022). "In addition, in the in-house cohort, CDCP1 was upregulated in the tumor tissues of patients who died during the follow-up processes." (PMID 36090897, 2022).